EZH2 (enhancer of zeste 2 polycomb repressive complex 2 subunit)
Diseases named in the same sentence as EZH2 in open-access papers (continued):
Sharing a sentence is not in itself a finding about the gene and the disease.
tumor (continued). "Interestingly, the expression of other BAF complex subunits like BRM seems to determine the sensitivity of tumours with BAF subunit mutations to EZH2 inhibition, suggesting BRM expression as a possible biomarker for therapeutic response." (PMID 30898143, 2019). "In general, lower EZH2 expression could be linked to higher tumor aggressiveness as advanced tumors (UICC III and IV, or tumors with lymph node or distant metastases) showed lower EZH2 expression." (PMID 31317325, 2019). "We further propose that, independent of the used scoring system, a remarkable loss of EZH2 from tumor center to the invasion front could be a suitable prognosticator of worse prognosis in daily routine." (PMID 31317325, 2019). "EZH2 expression is associated with tumor grade and aggressiveness of the disease." (PMID 29396474, 2018). "Moreover, transcriptional activation of EZH2 was associated with aberrant methylation of other tumor-related genes and DNMT3A upregulation in HNSCC." (PMID 30469511, 2018). "During tumor progression, Ezh2 inhibition amplified vulnerabilities associated with acute inflammatory transcription as revealed by sensitivity of treated tumor cells to inhibition of the cellular machineries involved in proteostasis and RNA synthesis and, indirectly, of the NF-κB pathway." (PMID 30487290, 2018). "These bioinformatic analyses also identified several potential transcriptional activators that could drive the expression of de-repressed PRC2 target genes in Ezh2-deficient tumours." (PMID 29959321, 2018). "However, the association of EZH2 expression levels with the biological behaviour of tumours is contradictory." (PMID 30542123, 2018). "Additionally, EZH2 is clinically associated with tumor progression and multiple metastatic features, and epigenetically restrained a subset of miRNA in human HCC." (PMID 30100882, 2018). "We found that overexpression EZH2 in UM is associated with adverse clinical outcome, hence, it might able to play a part in therapeutic target for reducing the tumor metastasis and improving survival time of UM patients." (PMID 29100322, 2017). "Interestingly, EZH2 expression has previous been linked with both increased growth and metastasis within tumours, whereas our model is predicated on a slowly proliferative cell phenotype." (PMID 28119061, 2017). "According to these studies, the oncogenic and tumor suppressive roles of EZH2 in cancer progression depend on its associated targets, post-translational modifications such as phosphorylation and methylation, and the cancer microenvironment such as hypoxia status." (PMID 28561778, 2017). "EED loss may be the key to maintain an EZH2 high/H3K27me3 low state in other tumour types, or even in normal cells such as the oesophageal epithelium, and will warrant more study in the future." (PMID 28387316, 2017). "This might reflect either a dose-dependent effect of the mutated EZH2 level on H3K27 methylation, or the proportion of sub-clones carrying an EZH2 mutation within the tumor." (PMID 28430172, 2017). "Similarly, Adhikary G and colleagues considered SCC-13-derived spheroids to be epidermal CSCs (ECS cells) and demonstrated that EZH2 can promote the survival, invasion and tumor formation capacity of ECS cells, with associated increases in H3K27me." (PMID 28415635, 2017). "The mutation-based dual role suggests that EZH2 may serve as either an oncogene or tumor-suppressor gene depending on the cellular context." (PMID 28701722, 2017).
tumor (continued). "EZH2 up-regulation has been implicated in acute pancreatitis, where it promotes tissue repair through regenerative proliferation of progenitor cells, resulting in impaired pancreatic regeneration and accelerating Kras-driven neoplasia." (PMID 26848980, 2016). "This phenotype is associated with aberrant EZH2 expression in tumor cells." (PMID 26497210, 2016). "Moreover, EZH2 expression is associated with a high proliferation rate and aggressive tumor subtypes of cancer." (PMID 27172794, 2016). "Numerous studies suggest that up-regulation of H3K27me3 levels by EZH2 overexpression or mutation could silence tumor suppressors connected to promoting tumor growth and metastasis." (PMID 26868841, 2016). "Of note, patient 1687 seems to present a clonal mutation of EZH2 but low tumor content." (PMID 25762637, 2015). "Finally, we analyzed the consequences of EZH2 deletion on orthotropic tumor growth in mammary fat pads of immune-deficient host mice." (PMID 26637281, 2015). "Furthermore, there are evident associations between EZH2 and markers of tumor cell proliferation, as well as the phenotypes of aggressive diseases." (PMID 26378045, 2015). "It has been reported that EZH2 is closely associated with tumor progression and metastasis." (PMID 25869101, 2015). "On the basis of increasing integrated research and experimental evidence, it is now fully elucidated that EZH2 plays a central role in cancer transformation, and its overexpression is associated with tumor cell anti-apoptosis, invasiveness, chemo-resistance in human cancers including HNSCC." (PMID 26378043, 2015). "However, we found that copy number-driven, proliferation-independent expression of EZH2 displays an inverse association with tumor outcome, with low expression of EZH2 being linked to a poor prognosis." (PMID 26637281, 2015). "Several recent preclinical studies demonstrated that potent and selective S-adenosyl-methionine-competitive small molecule inhibitors of EZH2 such as E7438 (EPZ-6438), GSK-126 or CPI-360 eliminate tumor growth in GCB-DLBCL models with activating EZH2 mutations." (PMID 26654227, 2015). "It is expected that tumor types in which EZH2 gain-of-function mutations occur (e.g., DLBCL and FL) as well as tumors harboring mutations in SWI/SNF components might benefit from these molecules." (PMID 26637281, 2015). "The association of EZH2 with tumor differentiation may be related to the major biological function of EZH2 which is to maintain the undifferentiated stage of cells." (PMID 25226601, 2014). "In EZH2 transgenic mouse model, ovexpression of EZH2 in mammary epithelial cells using the mouse mammary tumor virus long terminal repeat causes epithelial hyperplasia, highlighting the potential role of EZH2 in tumor progression." (PMID 25520914, 2014). "The effects of the EZH2 inhibitor were anti-proliferative, as demonstrated by the retardation of tumor growth associated to a reduction of the proliferative marker Ki67 in tumor xenografts, and led to de novo expression of fibers positive for Myosin Heavy Chain (MHC) compared to vehicle treatment." (PMID 24575771, 2014). "Furthermore, EZH2 has oncogenic activity in multiple cancers, but inactivating mutations lead to the tumor suppressor activity of EZH2 in myeloid malignancies." (PMID 25360999, 2014). "Tumor cells and cancer-associated fibroblasts were positive for EZH2 immunohistochemical staining." (PMID 25025074, 2014). "Thus, EZH2 overexpression represses expression of the product of a tumor suppressor gene called E cadherin that causes cells to stick to each other." (PMID 24313165, 2013). "Thus, EZH2 also contributes to malignant behaviors of EOC by altering EOC-associated tumor microenvironment through promoting angiogenesis." (PMID 23494175, 2013). "We found EZH2 immunoreactivity to be positively associated with tumour stage (r = 0.89, p<0.05)." (PMID 23874688, 2013).
tumor (continued). "In addition, there was a significant reduction in CD31-positive vessels in EZH2 knockdown tumors compared to control tumors, suggesting that the loss of angiogenesis subsequently inhibits tumor growth." (PMID 24294976, 2013). "This last sample (76.1) could not be properly subtyped at the time of diagnosis due to insufficient number of tumor cells, but a subsequent sample tested from the same case had a diagnosis of FL, also positive for the same EZH2 mutation." (PMID 23361872, 2013). "Later, groups found that EZH2 was also significantly associated with tumor cell proliferation." (PMID 23133536, 2012). "Pearson correlation showed a significantly positive correlation between the percentage of EZH2 expressing cells and that of proliferating cells (p = 0.001, R = 0.74), demonstrating a strong association of EZH2 with tumor proliferation in both metastatic lymph nodes and primary tumors in situ." (PMID 23251464, 2012). "EZH2 and H3K27me3 scores also exhibited significant association with tumor size." (PMID 23110793, 2012). "Therefore, we decided to examine the expression of EZH2 by immunohistochemistry in various histological types of hepatic tumors and tumor-like lesions to investigate its discriminatory diagnostic value." (PMID 22809481, 2012). "However, Ki-67 was a superior predictor of tumor-associated death, since the hazard ratios referring to high EZH2, H3K27me3, and Ki-67 expression were 4.48, 5.65, and 6.32, respectively." (PMID 23110793, 2012). "As polycomb group proteins are known to be vitally involved in transcriptional control and carcinogenesis in several human tumours, EZH2 may be less susceptible to the development of immune escape variants." (PMID 21407224, 2011). "Moreover, the expression of EZH2 has been linked to tumor aggressiveness and metastatic potential, and has been linked to a poor overall patient prognosis." (PMID 22053850, 2011). "EZH2 has been linked to proliferation in several tumour types." (PMID 19099573, 2008). "Notably, EZH2 has been linked to tumor progression, and further exploration of its specific mechanisms may shed light on its role in cancer development and enhance our understanding of potential therapeutic targets." (PMID 40678068, 2025). "Since EZH2 KO primary tumors likely have to undergo similar processes to WT cells to metastasize, our results suggest that EZH2 deficiency in the former may not only negatively affect tumor cell mobilization and survival, but also the processes leading to metastasis." (PMID 38791429, 2024). "Moreover, elevated levels of EZH2 were associated with growth, metastasis, and tumor stage in PTC." (PMID 37917782, 2023). "Thus, EZH2 suppresses T-cell-associated tumor immunity to promote progression of HCC." (PMID 37268997, 2023). "In addition, the tumor suppression effect caused by RCC1 knockdown could be rescued by EZH2 overexpression in vitro." (PMID 37747077, 2023). "Therefore, EZH2 inhibitors can enhance tumor cell immunogenicity by reshaping the epigenetic landscape of cancer cells and favoring the expression of genes associated with both the presentation of new antigens and the recruitment of anti-tumor immune cells." (PMID 36900330, 2023). "An aberrant expression of EZH2 enhances cell proliferation, which may cause tumor development." (PMID 36712863, 2022). "Thus, we speculated that EZH2 inhibitor treatment might promote tumor metastasis in association with augmented tumor angiogenesis through TAMs-secreted VEGF." (PMID 36038549, 2022).
tumor (continued). "As our previous studies showed that conditional loss of EZH2 in the uterus elicits epithelial stratification, we asked the question of whether uterine epithelial stratification occurred in Ptend/d; Ezh2d/d mice during tumor development." (PMID 35269532, 2022). "EZH2 inhibitors downregulate the level of ChK1 phosphorylation through an unknown mechanism, thereby inhibiting the DNA damage response, and ChK1 inhibitors are more sensitive in EZH2-deficient tumor cells, more apparently inducing cell apoptosis." (PMID 36263120, 2022). "Thus, the downregulation of both SWI/SNF and PRC2 complex factors but upregulation of HDAC7 suggests EZH2-associated platinum resistance may reflect increased tumor stemness." (PMID 34140011, 2021). "EZH2 can also promote the development and progression of cancer via chromatin modification including the epigenetic activation of the oncogenic signaling cascade and silencing of tumor suppressor genes; it has been implicated in cell proliferation, differentiation, invasion, and metastasis." (PMID 33276757, 2020). "Thus, we hypothesized that ARID1A mutation status may be involved in an anti-tumor effect of WHSC1 suppression similar to EZH2." (PMID 31092221, 2019). "We further investigated the difference in EZH2 levels between tumours and benign tissues in Chinese patients with UC and explored whether elevated EZH2 expression could be a valuable biological marker associated with aggressive and invasive potential of UC of the bladder." (PMID 30542123, 2018). "Loss of KDM6A activity may sensitize tumor cells to demethylating agents such as EZH2 inhibitors." (PMID 29989027, 2018). "Additionally, the status of the cdkn2a locus of an individual tumor might predict its response to Ezh2 loss." (PMID 30080881, 2018). "Ezh2 peaks in Cluster 1 and 2 also overlapped with promoters and H3K27me3 in human NPCs, consistent with the idea that these Ezh2 and H3K27me3 peaks likely represent Ezh2 peaks commonly found in tumor-initiating cells before the introduction of H3.3K27M mutation." (PMID 29932419, 2018). "Data from pre-clinical studies of EZH2 inhibitor E7438 in MM cell lines and mice model showed that EZH2 inhibition causes a global reduction in H3K27me3 methylation in a dose dependent manner, which in turn led to re-expression of tumor suppressor genes in some of the cell lines." (PMID 30555699, 2018). "Also, a direct involvement of PRC2 components in the progression from neurofibroma to MPNST has been demonstrated showing that, surprisingly, EZH2 works as a tumor suppressor, and the detection of the loss of H3K27 trimethylation has entered the clinical practice to help in the diagnosis of MPNST." (PMID 30416982, 2018). "Thus, EZH2 may play a critical role to regulate the G1/S phase into G2 phase through the cell cycle arrest, which is associated with proliferation during tumor progression and leads to poor prognosis." (PMID 27706111, 2016). "Moreover, EZH2 is implicated in promoting tumor angiogenesis." (PMID 26683709, 2016). "Interestingly, it has been reported that EZH2 polymorphisms may contribute to susceptibility of tumor development and predict overall survival in some cancers and may have also contributed to progression of the disease in this patient." (PMID 27993143, 2016). "The authors suggested that despite the compromised proliferative capacity in the setting of EZH2 loss, induction of cytokine production in the tumor microenvironment might lead to expansion of the dysplastic myeloid clones while upregulation of EZH2 can promote progression to AML." (PMID 27793053, 2016). "Of note, a recent study investigating the role of Ezh2 in a Brca1 deficiency-based model of mammary tumorigenesis found that deletion of Ezh2 shortens the latency of tumor formation, further reinforcing the view that the enzyme might inhibit breast tumorigenesis." (PMID 26637281, 2015).
tumor (continued). "Importantly, GOF mutations render DLBCL cell lines exquisitely sensitive to catalytic inhibition of EZH2 activity, suggesting that EZH2 activity is crucial for these tumor types and opening up the possibility of EZH2 inhibitor-based therapy for patients with these mutations." (PMID 25671303, 2015). "Therefore, the molecular mechanisms of DZNep might be more complex than our current knowledge base, which associates the downregulation of EZH2 with the ability of DZNep to induce tumor cell death." (PMID 24852755, 2014). "Moreover, EZH2 is implicated in promoting tumour angiogenesis." (PMID 22187039, 2012). "Therefore, truncated or missense mutations in EZH2 observed in myeloid malignancies are supposed to be inactivating mutations, and EZH2 may be a tumor suppressor in this context." (PMID 21795762, 2011). "Although numerous EZH2 inhibitors have been developed for tumor treatment, their clinical efficacy in solid tumors remains limited." (PMID 41544165, 2026). "c-MYC and EZH2 expression was assessed immunohistochemically in tumor samples and evaluated by nuclear staining intensity and the percentage of stained tumor cells." (PMID 41928013, 2026). "Dual targeting of Wnt/β-catenin and EZH2 diminished diverse cell states by restoring bivalency and effectively blocked tumor growth." (PMID 41842971, 2026). "By extracting and analyzing proteins from tumor tissues, we demonstrated that crotonate-treated tumors exhibited elevated global crotonylation levels and reduced EZH2 protein expression." (PMID 41544165, 2026). "Dysregulation of histone-modifying enzymes, such as EZH2, can result in modified expression of oncogenes and tumor suppressors, hence leading to epigenetic heterogeneity within the tumor." (PMID 41562920, 2026). "Histone methylation: EZH2-driven H3K27me3 inhibits tumor suppressors, lineage regulators, and immune-related genes." (PMID 41596524, 2026). "The presence of accessible cysteines in TRIM28 and EZH2 further highlights the potential of this strategy in disrupting their interaction and reactivating silenced genes involved in tumor suppression." (PMID 41504013, 2026). "Immunohistochemistry revealed a markedly elevated Ki-67 proliferative index (> 90%), and genomic profiling identified pathogenic EZH2 and TET2 mutations with a high tumor mutational burden." (PMID 42088612, 2026). "Predicted tumor-Treg interaction patterns were stronger in CRPC and positively associated with EZH2 expression." (PMID 41710887, 2026). "In order to address this burden, enhancer of zeste homolog 2 (EZH2); an epigenetic regulator implicated in various cancers, has been an attractive target, due to promising tumor-suppressive effects in both preclinical and clinical studies." (PMID 41552643, 2026). "EZH2 plays a critical role in promoting tumor growth, metastasis, metabolism, and regulating antitumor immunity." (PMID 41544165, 2026). "At the chromatin level, EZH2-mediated H3K27 methylation inhibits tumor suppressors like PTEN and collaborates with PI3K signaling to promote oncogenic transcription." (PMID 41596524, 2026). "Emerging evidence suggests that SOX-2 and EZH-2 play critical roles in salivary gland carcinogenesis, being related to tumor cell stemness potential, along with accelerated tumor progression and unfavorable clinical outcomes." (PMID 42029612, 2026). "EZH2 overexpression or hyperactivation contributes to tumor progression, immune evasion, and therapeutic resistance." (PMID 42220432, 2026). "Tumors with enhanced EZH2 activity or stability frequently display immunosuppressive tumor microenvironments and are often resistant to immunotherapy." (PMID 41544165, 2026). "Our findings reveal the interdependent roles of EZH2 and Ca2+ signals in coordinating antigen-activated T-cell responses that mediate alloimmunity and tumor immunity." (PMID 42020715, 2026).